PTTG1 (PTTG1 regulator of sister chromatid separation, securin)
Diseases named in the same sentence as PTTG1 in open-access papers (continued):
Sharing a sentence is not in itself a finding about the gene and the disease.
seminoma (continued). "Since PBF is reported to mediate PTTG1 nuclear translocation, we wondered if this protein was involved in PTTG1 differential localization in three seminoma cell lines." (PMID 33430117, 2021). "We previously reported that in seminomas, PTTG1 was detected in the peripheral area of the tumor and in the leading infiltrative edge." (PMID 33430117, 2021). "A database interrogation revealed that exclusively in seminoma PTTG1 was localized in the nucleus compared with non-seminoma tumors." (PMID 33430117, 2021). "The results of the present research highlight the role of nuclear PTTG1 fraction on the invasive properties of human seminoma tumors." (PMID 33430117, 2021). "The present study strengthens the role of PTTG1 nuclear localization in promoting invasiveness and metastasis of seminoma cell lines." (PMID 33430117, 2021). "RNA interference and overexpression experiments were performed to address the PTTG1 role in seminoma invasiveness." (PMID 33430117, 2021). "Our data provide insights into the molecular characterization of seminoma, promoting PTTG1 as a prognostic marker useful in human seminoma clinical management." (PMID 33430117, 2021). "In particular, we evaluated the role of PTTG1 nuclear fraction in human seminoma-derived cell cultures." (PMID 33430117, 2021). "Previously, we found that PTTG1 nuclear localization was strongly correlated with MMP-2 activity in our seminoma in vitro model." (PMID 33430117, 2021). "Atlas database analysis revealed that PTTG1 was localized in the nucleus in seminoma compared with non-seminoma tumors, and that MMP-2 levels were significantly higher in seminomas." (PMID 33430117, 2021). "Preliminary reports demonstrated that most cells in seminoma express Pituitary-tumor-transforming-gene 1 (PTTG1), as well as Octamer-binding transcription factor 4 (OCT-4) and Krüppel-like factor 4 (KLF-4)." (PMID 34209730, 2021). "Of interest, PTTG1 protein is differentially expressed in the seminoma cell lines, with TCAM2 cells presenting the lowest levels." (PMID 33430117, 2021). "We previously demonstrated that PTTG1 is mainly localized at the neoplasm periphery and infiltration area of seminoma." (PMID 33430117, 2021). "Of interest, we validated the in vivo role of nuclear PTTG1 in seminoma via interrogation of the Atlas database of human testicular cancer." (PMID 33430117, 2021). "Of interest, analysis of the Atlas database of testicular tumors supported in vivo the role of PTTG1 in seminoma." (PMID 33430117, 2021). "In the current study, we now demonstrate that PTTG1 is highly expressed in these three seminoma cell lines." (PMID 33430117, 2021). "This pilot study provides the first identification of a cell population in seminoma characterized for being OCT4, KLF4, and PTTG1 positive cells in seminoma, associated with cancer invasiveness." (PMID 31572301, 2019). "In this study we confirmed that some cells in seminoma express PTTG1 and demonstrated that it is a sub-population of tumor stem cells OCT4- and KLF4- positive cells." (PMID 31572301, 2019). "This is the first identification of a cell population in seminoma characterized for being OCT4, KLF4, and PTTG1 positive cells in seminoma, associated with cancer invasiveness." (PMID 31572301, 2019). "In this pilot study, we compared the combined expression of PTTG1 with KLF4 and OCT4 in seminoma, in order to validate our hypotesis that PTTG1 marks a specific population of stem cells in neoplastic tissue, strictly related with tumor." (PMID 31572301, 2019). "Indeed, we demonstrated that PTTG1’s nuclear localization was more pronounced in the seminoma periphery, the area that is more inclined to be highly invasive." (PMID 38069214, 2023). "Furthermore, we analyzed the colocalization of PTTG1/SPTBN1 in human specimens from patients who underwent therapeutic orchiectomy for seminomas." (PMID 38069214, 2023).
seminoma (continued). "Moreover, we further correlated the nuclear localization of PTTG1 with the aggressive phenotype in three different seminoma cell lines (JKT-1, SEM-1, and TCAM2)." (PMID 38069214, 2023). "This PTTG1/SPTBN1 interaction could be negatively affected during seminoma tumor invasion, and we reported a progressive PTTG1 nuclear localization in this setting." (PMID 38069214, 2023). "We therefore wondered if SPTBN1 could act as a cytoplasmic scaffold of PTTG1 in seminoma and be one the factors responsible for its subcellular localization." (PMID 38069214, 2023). "Since the three human seminoma cell lines showed different aggressive behaviours that correlated with PTTG1 nuclear levels, we speculated that this specific subcellular localization could mark distinct seminoma stages." (PMID 38069214, 2023). "Taken together, these findings led us to hypothesize a model in which spectrins retain PTTG1 outside of the nucleus, thereby impairing its oncogenic activity in seminoma." (PMID 38069214, 2023). "Therefore, this would emphasize the eligibility of SPTBN1 as a novel prognostic factor, along with PTTG1, for the clinical management of seminoma tumors." (PMID 38069214, 2023). "To this aim, we evaluated the subcellular distribution of these proteins through confocal microscopy, and ex vivo, we confirmed that the colocalization of PTTG1/SPTBN1 occurs to a significantly higher extent in the area of the seminoma showing greater cytoplasmic PTTG1 levels." (PMID 38069214, 2023). "This prompted us to identify the factors responsible for the progressive nuclear translocation of PTTG1 in order to uncover new players in seminoma cancer progression that may be useful for prognosis." (PMID 38069214, 2023). "Interestingly, the analysis showed a highly significant lower level of E-CAD in seminoma samples compared to nonseminoma samples, supporting the role of nuclear PTTG1 in driving E-CAD transcriptional repression in human seminomas." (PMID 36230799, 2022). "To verify that the observed phenomenon relies on PTTG1, we analyzed ZEB1 levels in seminomas, since an augmented expression in this subclass could belittle PTTG1 role." (PMID 36230799, 2022). "Furthermore, we confirmed the role of nuclear PTTG1 in human seminoma taking advantage of the Atlas database of TGCTs." (PMID 36230799, 2022). "Here, we focused on the role of PTTG1 in the EMT process in seminoma." (PMID 36230799, 2022). "This phenomenon is not coupled with an increase in ZEB1 levels in seminoma, supporting the hypothesis that nuclear PTTG1 cooperates with ZEB1-dependent E-CAD repression in human seminoma tumors." (PMID 36230799, 2022). "Here, we investigated the key players involved in PTTG1-mediated EMT in human seminoma." (PMID 36230799, 2022). "To determine whether the role of PTTG1 observed in cell lines has a translational impact in human seminomas, we wondered whether the PTTG1/ZEB1/E-CAD axis was confirmed in human testicular tumors." (PMID 36230799, 2022). "Therefore, the results of this research represent a further step in understanding the partners and crosstalk of PTTG1 that contribute to its oncogenic activity and represent potential prognostic factors in human seminoma." (PMID 36230799, 2022). "Therefore, we investigated the role of PTTG1 in EMT in human seminoma using an in vitro and in vivo model and through Atlas database interrogation." (PMID 36230799, 2022). "Interestingly, PTTG1-positive cells were also present in the leading infiltrative edge of the seminomas." (PMID 33430117, 2021). "Overall, these results suggest that other players beyond PBF could determine nuclear PTTG1 localization in some seminoma tumors." (PMID 33430117, 2021). "It is tempting to speculate that the three cell lines, bearing different PTTG1 nuclear levels, could resemble distinct stages of seminoma." (PMID 33430117, 2021).
seminoma (continued). "Ongoing studies are focused on the identification of PTTG1 PTMs or cytoplasmic interactors that inhibit its nuclear translocation in order to uncover new prognostic/therapeutic factors useful in the clinical management of seminomas." (PMID 33430117, 2021). "Importantly, this analysis further demonstrated a significant higher level of MMP-2 in seminomas compared to non-seminoma tumors, supporting the role of PTTG1 nuclear activity in driving MMP-2 levels and hence in promoting invasiveness of these tumors." (PMID 33430117, 2021). "Above all, in seminomas, we reported a differential PTTG1 localization." (PMID 33430117, 2021). "Interestingly, PTTG1 showed a cytoplasmic/membranous/nuclear localization (C/N) in all seminoma specimens while in non-seminoma samples, it mainly localized in the cytoplasmic/membranous compartment (C)." (PMID 33430117, 2021). "Here, we investigate the PTTG1 role on the invasive properties of seminoma." (PMID 33430117, 2021). "The aim of the present work was to investigate the role of PTTG1 in seminoma cancer progression." (PMID 33430117, 2021). "In order to validate in vivo the role of PTTG1 in seminoma, we wondered whether PTTG1, PBF, and MMP-2 showed specific behavior in human testicular tumors." (PMID 33430117, 2021). "Further investigation is needed to elucidate if a functional abrogation of PTTG1 might be used in order to offer new therapeutic approaches in the clinical workout of seminoma." (PMID 31572301, 2019). "Formalin-fixed and paraffin-embedded testicular tissues by 5 patients who underwent an orchidectomy for seminoma have been collected and immunofluorescence analysis was performed using antibody rabbit monoclonal PTTG-1 and mouse monoclonal OCT4 or mouse monoclonal KLF4 antibody." (PMID 31572301, 2019). "Moreover, in the zones of seminoma infiltration we demonstrated the presence of clusters of PTTG1-positive cells." (PMID 31572301, 2019). "Furthermore, in the peripheral area of seminoma, PTTG1 was mostly detected as localized in the nucleus, whereas in the central nucleus of seminoma, PTTG1 was mainly expressed in cytoplasm." (PMID 31572301, 2019). "The expression in seminoma stem cells of PTTG1 may permit them to invade surrounding tissues and to lead to neoplastic angiogenesis." (PMID 31572301, 2019). "In this pilot study, we compared the combined expression of PTTG1 with KLF4 and OCT4 in seminoma, in order to validate our hypothesis that PTTG1 could mark a specific subset of neoplastic stem cells, strictly related with tumor." (PMID 31572301, 2019). "Indeed, we previously reported that nuclear PTTG1 was a specific feature of the seminoma histotype." (PMID 38069214, 2023). "Thus, it is presumable that the increased nuclear expression of PTTG1 could represent an eligible prognostic factor in seminomas." (PMID 36230799, 2022). "Therefore, we aim to investigate in vitro the role of PTTG1 on the invasive properties of seminoma." (PMID 33430117, 2021). "Of interest, in seminomas, PTTG1 was localized in the cytoplasm in the central area of the tumor while in the periphery it was mainly localized in the nuclei, leading us to hypothesize that the more invasive-prone cancer area requires a nuclear localization of this securin." (PMID 33430117, 2021). "Taken together, these findings support the role of PTTG1 nuclear localization in promoting invasiveness and metastasis, leading to the hypothesis that nuclear PTTG1 eligibility is a potential prognostic factor for seminomas." (PMID 33430117, 2021). "Overall, these data strongly suggest that nuclear PTTG1 may be a prognostic factor in seminomas." (PMID 33430117, 2021). "Moreover, analysis of the Atlas database revealed that PBF levels were lower in seminomas compared to non-seminoma tumors, supporting the hypothesis that other players could determine nuclear PTTG1 localization in seminoma." (PMID 33430117, 2021).
seminoma (continued). "The in vitro human seminoma cellular model represented by the three cell lines (JKT-1, SEM-1, and TCAM2) showed a decreasing gradient of nuclear PTTG1, and this feature correlates with the aggressive behavior of the cell lines." (PMID 38069214, 2023). "In order to translate these results to clinical practice, we verified the interplay between PTTG1 and SPTBN1 in human seminoma specimens from patients who underwent therapeutic orchiectomy." (PMID 38069214, 2023). "Of note, in our seminoma cellular models, we found that PTTG1 and SPTBN1 interact almost exclusively in TCAM2 cells in which PTTG1 is more cytoplasmic in comparison to the other cell lines." (PMID 38069214, 2023). "The new findings of our research suggest that in human seminoma, SPTBN1 plays a key role as a cytoplasmic constraint for PTTG1, impairing its nuclear oncogenic activity." (PMID 38069214, 2023). "We previously showed the role of nuclear PTTG1 in promoting invasiveness, through its transcriptional target MMP2, in seminoma in vitro models." (PMID 36230799, 2022). "To further detail the molecular mechanism behind PTTG1/ZEB1 cooperation, we carried out immunoprecipitation in both an unrelated cellular model, 293-T, and in a seminoma cell line." (PMID 36230799, 2022). "Here, we demonstrated, for the first time in seminoma cells, an E-CAD decrease upon dose-dependent PTTG1 overexpression." (PMID 36230799, 2022). "Taken together, these data support the role of PTTG1/ZEB1 interplay in driving E-CAD repression in vivo, and hence in promoting EMT in specific areas of human seminoma tumors." (PMID 36230799, 2022). "Taken together, these results show for the first time a new co-repressional platform in seminoma cells, indicating that PTTG1/ZEB1 cooperation is essential for PTTG1 to exert its E-CAD regulation." (PMID 36230799, 2022). "RNA depletion and overexpression experiments were performed to verify the role of PTTG1/ZEB1 in E-Cadherin repression and seminoma invasiveness." (PMID 36230799, 2022). "Analysis of Atlas in vivo data strongly supported these results, revealing an exclusive PTTG1 nuclear localization and a concomitant increase of MMP-2 levels in seminoma compared to non-seminoma tumors." (PMID 33430117, 2021). "Analysis of human testicular tumors from the Atlas database revealed an exclusive PTTG1 nuclear localization and a concomitant increase of MMP-2 levels in seminoma compared to non-seminoma tumors." (PMID 33430117, 2021). "Since it has been reported that PTTG1 enhances MMP-2 expression and activity, we investigated metalloproteinases secretion/activity in the seminoma cell lines by zymography." (PMID 33430117, 2021). "Immunoblot analysis of whole cell extracts show that PTTG1 was overexpressed in the seminoma cell lines compared to PC3 cells, prostatic adenocarcinoma derived cells in which PTTG1 is reported to be upregulated." (PMID 33430117, 2021). "We hypotyzed that PTTG1 marks a population of neoplastic cells, both in CIS and in seminoma, so linking CIS to seminoma carcinogenesis." (PMID 31572301, 2019). "According to our model, the interaction between PTTG1 and SPTBN1 could be impaired during seminoma development, leading to a progressive PTTG1 nuclear localization." (PMID 38069214, 2023). "Finally, to further confirm the PTTG1/ZEB1 interplay from a clinical point of view, we analyzed the molecular interaction via immunoprecipitation and confocal microscopy of human seminoma specimens obtained from patients who underwent therapeutic orchidectomy." (PMID 36230799, 2022). "In addition, using immunoprecipitation, we demonstrated the interaction of PTTG1 and ZEB1 in human seminoma specimens from patients that underwent therapeutic orchidectomy for seminoma." (PMID 36230799, 2022).
seminoma (continued). "To this end, we modulated PTTG1 protein levels in JKT-1 and SEM-1 seminoma cell lines, which show a more aggressive phenotype among the seminoma lines, and we evaluated the expression of E-CAD, since it is known that its decreased expression is one of the earliest steps in the EMT process." (PMID 36230799, 2022). "Previously, we demonstrated that PTTG1 has a predominant nuclear localization in seminomas compared to nonseminomas." (PMID 36230799, 2022). "Importantly, we demonstrated the physical interaction of PTTG1 and ZEB1 in human seminoma specimens." (PMID 36230799, 2022). "The interrogation of this database revealed that in seminoma tumors, where PTTG1 is more localized in the nucleus than in the nonseminoma subtype, a significantly lower E-CAD expression is observed compared to the observations of nonseminomas." (PMID 36230799, 2022). "The analysis demonstrates a significantly higher level of MMP-2 in seminomas compared to non-seminoma tumors, supporting the role of PTTG1 nuclear activity in driving MMP-2 levels and hence in promoting invasiveness of seminoma tumors." (PMID 33430117, 2021). "Using the Atlas database, first we analyzed PTTG1 RNA levels in seminoma (S) versus non-seminomas (N-S) testicular tumors and showed that PTTG1 levels were significantly lower in seminomas." (PMID 33430117, 2021). "This analysis revealed that PTTG1 was localized in the nucleus exclusively in seminoma, despite its lower levels in this group, compared to non-seminoma tumors." (PMID 33430117, 2021). "An interrogation of the same Atlas database, to evaluate MMP-2 levels in seminoma compared with non-seminoma tumors, showed a significant higher level of MMP-2 in seminoma samples, supporting the role of PTTG1 nuclear transcriptional activity in driving MMP-2 levels." (PMID 33430117, 2021). "We previously examined firstly the expression of PTTG1 in CIS and seminomas." (PMID 31572301, 2019). "Therefore, studies should be performed to investigate whether the impairment of seminoma cell motility and migration by OLE could involve PTTG1 expression." (PMID 35684123, 2022). "ZEB1 levels were significantly lower in seminomas than in nonseminomas, supporting our hypothesis that PTTG1’s cooperation with ZEB1 is crucial in the transcriptional repression of E-CAD in human seminomas." (PMID 36230799, 2022). "Finally, we previously demonstrated the expression of PTTG1 in CIS and seminomas." (PMID 31572301, 2019). "Moreover, we demonstrated that this phenomenon has a functional impact on seminoma tumor progression; indeed, in the 3D sphere-forming assay, we found that the downregulation of SPTBN1 led to an increase in the diameter of TCAM2 spheres, which was induced by PTTG1 nuclear translocation." (PMID 38069214, 2023). "Further investigation are needed to extend the number of clinical cases investigated, to analyze the co-localization of PTTG1 with MMP2, MMP9, VEGF and to clarify if a functional abrogation of PTTG1 might represent a novel therapeutic approaches in the clinical management of seminoma." (PMID 31572301, 2019). "Since PBF mediates PTTG1 nuclear translocation, we would expect higher PBF levels in seminoma specimens compared to non-seminoma." (PMID 33430117, 2021).